EPHA2 (EPH receptor A2)
Diseases named in the same sentence as EPHA2 in open-access papers (continued):
Sharing a sentence is not in itself a finding about the gene and the disease.
gastric cancer (52 papers, 2013 to 2025). A primary or metastatic malignant neoplasm involving the stomach. "Higher levels of EphA2 and ephrinA1 are associated with poorer survival rates in esophageal and gastric cancers." (PMID 39839790, 2024). "The humanised anti-EphA2 mAb DS-8895a binds the extracellular juxtamembrane region of EphA2, and inhibits tumour development in EphA2-positive human breast and gastric cancer models, causing antibody-dependent cellular cytotoxicity (ADCC)." (PMID 36830852, 2023). "In gastric cancer cells, cancer‐associated fibroblasts over-expressing EphA2 promote VM formation by activating the EphA2‐PI3K pathway." (PMID 35595748, 2022). "In gastric cancer, EphA2 interacts with and directly phosphorylates YAP, which causes YAP stabilization and its persistent presence in the nucleus." (PMID 35096972, 2021). "Treatment with DS-8895a of EphA2-positive breast and gastric cancer cells was shown to partially inhibit ephrin A1-associated EphA2 phosphorylation." (PMID 32811512, 2020). "In this study, we identified ALW, as an EphA2 small-molecule inhibitor, can cause gastric cancer cell regression both in vitro and in vivo." (PMID 30451837, 2018). "We previously reported that EphA2 overexpression is associated with poor prognosis for gastric cancer patients and promotes the epithelial-mesenchymal transition (EMT) through the Wnt/β-catenin pathway in gastric cancer cells." (PMID 30451837, 2018). "We found that EphA2 expression levels were upregulated in gastric cancer and associated with chemotherapy sensitivity." (PMID 28624791, 2017). "After transfection of the oxaliplatin-resistant gastric cancer cell line SGC-7901/L-OHP with EphA2 siRNA, we tested the susceptibility of these cells to L-OHP using an MTT assay." (PMID 28624791, 2017). "The EPHA2 gene encoding erythropoietin-producing hepatocellular A2 (EphA2) plays a significant role in cancer progression through neovascularization while silencing of EPHA2 in human gastric cancer cells in vitro and in vivo decreased cell invasion, thus inhibiting cancer cell progression." (PMID 34299042, 2021). "Expressions of both EphA2 and ephrinA1 on the basis of the mRNA level or immunohistochemical analysis have been demonstrated to be higher in gastric cancer than in normal tissue, and EphA2 was significantly associated with poor survival, whereas ephrinA1 was not." (PMID 23738943, 2013). "In gastric cancer, EphA2 can promote tumor cell progression by activating the Wnt signaling pathway." (PMID 37980165, 2023). "In gastric cancer, it promoted phosphorylation of EPHA2 and enhanced soluble Ephrin A1-mediated migration by modifying EPHA2 O-glycosylation." (PMID 35864552, 2022). "EPHA2 is reported to be overexpressed in gastric cancer and colorectal cancer and is involved in the increased invasion, migration, and prognosis of colorectal cancer cells." (PMID 35646067, 2022). "For example, EphA1 and EphA4 are upregulated in gastric cancer; EphA2 overexpression in mammary epithelial cells induces tumorigenesis and EphA8 stimulates the proliferation, invasion, and migration of gastric cancer cells." (PMID 35681118, 2022). "Direct targeting of EphA2 and its subsequent inhibition in gastric cancer and other tumor types (e.g., colorectal cancer) has been already successfully achieved to control Wnt-dependent, EphA2-mediated tumor proliferation." (PMID 35096972, 2021). "Anti-EPHA2 monoclonal antibody DS-8895a has been tested on esophageal and gastric cancer patients and EPHA3 antibody IIIA4 (Ifabotuzumab/KB004) on GBM cases and patients with hematologic malignancies." (PMID 34445116, 2021). "A group of researchers reported that miR-302b inhibits tumorigenesis by targeting EphA2 via EMT signaling cascade in gastric cancer, and others found that miR-125b-5p can function as a tumor suppressor in esophageal squamous cell carcinoma." (PMID 33098307, 2021).
gastric cancer (continued). "This novel EphA2-YAP interaction not only promotes gastric cancer growth but confers therapy resistance to these cells." (PMID 35096972, 2021). "miR-338 can inhibit EMT of gastric cancer cells through deactivation of Wnt/β-catenin signaling, targeting at EphA2." (PMID 34457026, 2021). "Previously, we reported that the overexpression of EphA2 was related to poor prognosis of patients with gastric cancer and promotes proliferation through Wnt/β‐catenin and Hippo pathways of gastric cancer cells." (PMID 33586348, 2021). "MiR-302b suppresses gastric cancer cell tumorigenesis and metastasis by regulating the EphA2/Wnt/β-catenin/EMT pathway." (PMID 34113619, 2021). "In gastric cancer cell lines, ligand-independent EphA2 activation upregulated N-cadherin and Snail, and the Wnt/β-catenin targets TCF4, Cyclin-D1, and c-Myc, thereby triggering epithelial-to-mesenchymal transition (EMT)." (PMID 33572284, 2021). "Further, in gastric cancer cells resistant to oxaliplatin, EphA2 was overexpressed and this correlated with EMT features." (PMID 33572284, 2021). "Recent studies considered the EPHA2 signalling pathway as a target of cancer therapy, and revealed that blocking EPHA2 reversed the acquired resistance of gastric cancer cells to afatinib and inhibit the proliferation of small cell lung cancer cells." (PMID 32732965, 2020). "Silencing of C1GALT1 decreased tyrosine phosphorylation of EPHA2, inhibited binding of Ephrin A1 to cell surfaces, and suppressed soluble Ephrin A1-induced migration in gastric cancer cells." (PMID 32005975, 2020). "In agreement, treatment with DS-8895a inhibits tumor growth in EphA2-positive human breast and gastric cancer xenografts in mice." (PMID 32811512, 2020). "Previous researchers have found that in gastric cancer EMT process can be promoted by EphA2 through activating Wnt/β-catenin signaling." (PMID 31956298, 2020). "Henrik Clausen’s team identified two O-glycosites, S277 and T429, on EPHA2 in gastric cancer cells using proteomics approaches." (PMID 32005975, 2020). "We also found that the effect of C1GALT1 knockout on cell invasiveness and peritoneal tumor growth of gastric cancer cells was phenocopied by EPHA2 knockdown." (PMID 32005975, 2020). "To know the in vitro effects of EPHA2 knockdown on gastric cancer cells, we analyzed cell viability, migration, and invasion using MTT, transwell migration, and Matrigel invasion assays, respectively." (PMID 32005975, 2020). "Our findings open novel insights into the role of O-glycosylation in EPHA2 functions and highlight C1GALT1 as a potential diagnostic and therapeutic target for gastric cancer." (PMID 32005975, 2020). "EPHA2 has been reported to promote epithelial–mesenchymal transition and silencing of EPHA2 inhibits gastric cancer cell growth and invasion." (PMID 32005975, 2020). "The effects of C1GALT1 knockdown or knockout on cell invasiveness in vitro and in vivo were phenocopied by EPHA2 knockdown in gastric cancer cells." (PMID 32005975, 2020). "One patient with EPHA2-positive gastric cancer achieved PR and 13 patients showed SD as best response." (PMID 31412935, 2019). "EPHA2 is overexpressed in many types of cancers, including 60% of gastric cancers and nearly 50% of esophageal cancers." (PMID 31412935, 2019). "To assess the clinical importance of EphA2 in the formation of VM, we investigated the correlation of EphA2 expression and VM incidence with clinicopathological features in 144 patients with gastric cancer." (PMID 30833656, 2019). "We previously reported that EphA2 promotes the epithelial–mesenchymal transition through Wnt/β-catenin signaling in gastric cancer." (PMID 30451837, 2018). "In this study, we discovered a novel mechanism by which EphA2 drives a feed-forward loop that regulates Wnt signaling; and targeting EphA2 significantly inhibits the proliferation of gastric cancer in vitro and in vivo." (PMID 30451837, 2018).
gastric cancer (continued). "To clarify the exact mechanisms of the EphA2 regulation of Wnt/β-catenin signaling in gastric cancer, we analyzed the structure of EphA2, and found that EphA2 shares a cysteine-rich domain (CRD) with Frizzled, a receptor for Wnt ligands." (PMID 30451837, 2018). "Data presented thus far provided strong evidence that EphA2 functions in promoting Wnt signaling in gastric cancer cells." (PMID 30451837, 2018). "We also observed similar changes in post-transfection expression of EphA2 and CTNNB1 (encoding β-catenin) with the EphA2-expressing vector in gastric cancer cells BGC823 and AGS, which indicated β-catenin is closely regulated by EphA2." (PMID 30451837, 2018). "c-MYC and CCND1 are downstream target genes of Wnt signaling, which suggests that EphA2 overexpression indeed enhances Wnt signaling in gastric cancer." (PMID 30451837, 2018). "Considering the significant roles of EphA2 and Wnt signaling in tumor development, we determined the impact of targeting EphA2 on gastric cancer by using a specific EphA2 inhibitor ALW-II-41-2727–29." (PMID 30451837, 2018). "A small molecular inhibitor of EphA2 potently inhibited the proliferation of gastric cancer in vitro and in vivo, including gastric cancer patient–derived xenografts." (PMID 30451837, 2018). "On the other hand, intratumoral injection of liposomal anti-EphA2 reduces 43.1% of tumor volume in gastric cancer cell which is need to be further analyzed in systemic administration to make it feasible for use in human." (PMID 29861465, 2018). "The sensitivity of gastric cancer cells to oxaliplatin following silencing of EphA2 was determined using the oxaliplatin-resistant gastric cancer cell line, SGC-7901/L-OHP." (PMID 28624791, 2017). "Preliminary receiver operating characteristic curve analysis demonstrated that the area under the curve ratios for detecting the soluble EphA2 fragment in pancreatic and gastric cancer patients were 0.89 and 0.88, respectively." (PMID 29072678, 2017). "The expression of EphA2 in gastric cancer tissues was significantly higher than that in adjacent normal gastric mucosa tissues (P < 0.05)." (PMID 28624791, 2017). "Conversely, silencing of EphA2 resulted in the inhibition of human gastric cancer SGC-7901 cell invasion both in vitro and in vivo." (PMID 28624791, 2017). "The expression of EphA2 in cancer tissues and adjacent normal gastric mucosa was analyzed in 120 patients with advanced gastric cancer using immunohistochemistry." (PMID 28624791, 2017). "The EphA2-silenced oxaliplatin-resistant gastric cancer cells (SGC-7901/L-OHP) migrated at a significantly reduced rate compared with the control group (P < 0.05)." (PMID 28624791, 2017). "In this study, the expression of EphA2 in cancer tissues and adjacent normal gastric mucosa was determined by immunohistochemistry in 120 patients with advanced gastric cancer." (PMID 28624791, 2017). "EphA2 showed significantly higher expression in gastric cancer tissues relative to adjacent normal gastric mucosa." (PMID 28624791, 2017). "The oxaliplatin-resistant gastric cancer cell line SGC-7901/L-OHP was transfected with EphA2 siRNA using Lipofectamine 2000." (PMID 28624791, 2017). "In this study, we observed that EphA2 expression significantly correlated with the expression of EMT markers in the oxaliplatin-resistant gastric cancer cell line SGC-7901/L-OHP." (PMID 28624791, 2017). "Erythropoietin-producing hepatocellular receptor A2 (EphA2) is upregulated in gastric cancer tissues and cells, which is accompanied by epithelial–mesenchymal transition (EMT)." (PMID 28624791, 2017). "In this study, we revealed that EphA2 was overexpressed in gastric cancer patients who received chemotherapy." (PMID 28624791, 2017). "EphA4 plays an important role in tumour progression and clinical outcomes, similar to EphA2, in patients with gastric cancer." (PMID 23738943, 2013).
gastric cancer (continued). "In gastric cancer cell lines that express EphA2, stimulation of EphrinA1 decreases EphA2 protein expression, but increases EphA2 phosphorylation." (PMID 23738943, 2013). "In gastric cancer, overexpression of EphA2, A4, and ephrinA1 has been reported by a few small studies." (PMID 23738943, 2013). "We therefore examined the relation between clinical outcomes and immunohistochemical expression of EphA2, EphA4, and ephrinA1 in gastric cancer." (PMID 23738943, 2013). "Meanwhile, miRNA-125a was reported to have oncogenic potential, which may promote the progression and invasion of gastric cancer through the regulation of EphA2, TAZ, and TEAD2 and myeloma progression through a reduction in DIS3 expression level." (PMID 40282476, 2025). "EphA2 drives chemotherapy resistance in gastric cancer cells by stabilizing YAP61." (PMID 37063424, 2023). "In addition, overexpression of EPHA2 can regulate the proliferation, migration, invasion, and morphology of gastric cancer cells by upregulating TCF4, CyclinD1, and c-Myc in the Wnt/β-catenin signaling pathway." (PMID 33834064, 2021). "EPHA2 has been shown to promote EMT in gastric cancer cells by modulating Wnt/β-catenin signaling." (PMID 34455105, 2021). "Likewise, EPHA2 upregulates the expression of CyclinD1 and promotes cell cycle progression, thereby enhancing the proliferation of gastric cancer cells." (PMID 33834064, 2021). "Likewise, ephrin A1-Fc increases EphA2 phosphorylation, decreases EphA2 protein expression, and inhibits growth in gastric cancer cells." (PMID 32811512, 2020). "In gastric cancer, miR‐302b exhibited anti‐tumour activity by reversing EphA2 regulation." (PMID 32233022, 2020). "In addition, the effects of C1GALT1 knockdown on cell invasiveness in vitro and in vivo were phenocopied by EPHA2 knockdown in gastric cancer cells." (PMID 32005975, 2020). "Although the downstream signaling pathways of Ephrin A1-EPHA2 in gastric cancer cells remain unclear, the effects of C1GALT1 and EPHA2 on phosphorylation of these molecules, including EPHA2, STAT3, AKT, ERK, FAK, and Src, were similar." (PMID 32005975, 2020). "The NCT02004717 trial was a two-step, study with step 1 evaluating a dose escalation cohort (six dose levels from 0.1 to 20 mg/kg) in patients with advanced solid tumors and step 2 assessing dose expansion in individuals with EphA2-positive esophageal and gastric cancers." (PMID 32811512, 2020). "There were two expansion cohorts, EPHA2-positive esophageal and gastric cancer patients." (PMID 32397088, 2020). "Based on this finding, we suggested that EphA2 might influence the growth of malignant tumor by promoting metastatic motility of gastric cancer cells during gastric tumorigenesis." (PMID 30833656, 2019). "Step 2 was a dose expansion cohort in EPHA2-positive esophageal and gastric cancer patients." (PMID 31412935, 2019). "Although EphA2 signaling is one of the key determinants in tumor microcirculation, its functional contribution to VM formation in gastric cancer remains unclear." (PMID 30833656, 2019). "However, the exact mechanisms of the EphA2 regulation of Wnt/β-catenin signaling in gastric cancer is unclear." (PMID 30451837, 2018). "Notably, our data indicated that ALW-induced gastric cancer cell regression was much significant in sh-NC tumors comparing to sh-EphA2 (i.e., EphA2-silenced) tumors, implying that tumor inhibition function of ALW is EphA2-dependent, at least partly." (PMID 30451837, 2018). "We treated the sh-NC (i.e. negative control shRNA) and sh-EphA2 cells with ALW or DMSO (as negative control) and evaluated whether the inhibitory effect of ALW on gastric cancer cells was dependent on the EphA2 level." (PMID 30451837, 2018). "Moreover, our results provide a potential epigenetic target for potential gastric cancer therapies that intervene with EphA2." (PMID 29273006, 2017).
gastric cancer (continued). "Moreover, silencing of EphA2 inhibited cell migration and invasion, and significantly enhanced the sensitivity of oxaliplatin-resistant gastric cancer cells to oxaliplatin." (PMID 28624791, 2017). "Therefore, EphA2 is an excellent candidate for the development of a targeted gastric cancer therapy that will improve chemosensitivity in tumors while maintaining resistance in normal cells." (PMID 28624791, 2017). "Our results suggest that high expression of EphA4 and EphA2 may play critical roles in tumor progression, metastasis, and outcomes in gastric cancer." (PMID 23738943, 2013). "Indeed, we could speculate that the high expression levels of EPHA2 observed in our analysis in aggressive epithelial cancers, such as pancreatic and gastric cancer, could reflect EMT activation in these histotypes." (PMID 34831119, 2021). "Furthermore, miRNA 520d-3p inhibits cell growth by reducing EphA2 expression in gastric cancer." (PMID 34872448, 2021). "EphA2 is frequently detected at low levels in various normal epithelial cells, and its overexpression has been investigated in solid tumours, including glioma, non‐small cell lung cancer, gastric cancer, renal cell cancer, colorectal cancer and endometrial cancer." (PMID 33586348, 2021). "Thus, our data identify EphA2 as an excellent candidate for gastric cancer therapy." (PMID 30451837, 2018). "EphA2 is a crucial oncogene in gastric cancer (GC) development and metastasis, this study aims to identify microRNAs that target it and serve as key regulators of gastric carcinogenesis." (PMID 29273006, 2017). "However, previous studies have not determined if the EMT in oxaliplatin-resistant gastric cancer cells can be regulated by EphA2, thereby affecting associated drug resistance." (PMID 28624791, 2017). "In gastric cancer, C1GALT1 promotes EPHA2 phosphorylation and enhances soluble Ephrin A1-mediated migration mainly by modifying the O-glycosylation of EPHA2, thereby affecting the cell invasiveness of gastric cancer cells." (PMID 38699634, 2024). "In a study using RT-PCR to identify the expressions of EPHA2 and EFNA1 in gastric cancer tissues and cell lines compared to normal tissues." (PMID 35309935, 2022). "In fact, EphA2 is a key player in EMT and its involvement in this process has been specifically described in gastric cancer." (PMID 34831119, 2021). "We screened out five overlapping Shc1-binding proteins (JUP, EPHA2, RASAL2, LYN, and SHCBP1), which were positively correlated with HER2 expression and were upregulated in gastric cancer." (PMID 33990570, 2021). "A physical and functional interaction between EphA2 and YAP was also shown to mediate resistance of gastric cancer (GC) cells to platinum in vitro and in vivo." (PMID 33572284, 2021). "Here, we show that EphA2, YES1, and ANXA2 form a signal axis, in which YES1 activated by EphA2 phosphorylates ANXA2 at Tyr24 site, leading to ANXA2 activation and increased ANXA2 nuclear distribution in gastric cancer (GC) cells." (PMID 33941853, 2021). "EPHA1, EPHA2, EPHA3, EPHA5, EPHB2 and EPHB4 expression has been reported as 2-fold higher in stromal cells isolated from gastric cancer tissues compared with normal gastric tissue stromal cells." (PMID 34445116, 2021). "To further confirm that C1GALT1 mediated its pro-migratory effect at least partly through EPHA2, we analyzed EPHA2 phosphorylation and cell migration in C1GALT1 knockdown, EPHA2 knockdown, or double knockdown gastric cancer cells." (PMID 32005975, 2020). "The morphological characteristics of VM and the role of EphA2 in the formation of VM were evaluated in 144 clinical samples of gastric adenocarcinoma and AGS gastric cancer cell line." (PMID 30833656, 2019). "In gastric carcinoma, erythropoietin producing hepatocellular (EphA2), a receptor tyrosine kinase (RTK) is found to be over expressed in 77.3% of gastric cancer patients and plays a vital role in metastasis via regulation of MMP-9 gene expression." (PMID 29861465, 2018).